RNU7-6P (RNA, U7 small nuclear 6 pseudogene)
Synonyms: U7.6
Gene: Small nuclear RNA gene on chromosome 20 (51,904,969 to 51,905,030, forward strand). Ensembl gene ENSG00000252654.
Homologues: Orthologues: chimpanzee U7 (97% identical), macaque U7 (95% identical). Paralogues in human: RNU7-13P (94% identical), RNU7-11P (92% identical), RNU7-22P (92% identical), RNU7-28P (92% identical), RNU7-41P (92% identical), RNU7-1 (90% identical), RNU7-18P (90% identical), RNU7-3P (90% identical), RNU7-45P (90% identical), RNU7-8P (90% identical), RNU7-25P (89% identical), RNU7-2P (89% identical), and 141 more.